GNG12 (G protein subunit gamma 12)
Diseases named in the same sentence as GNG12 in open-access papers (continued):
Sharing a sentence is not in itself a finding about the gene and the disease.
osteosarcoma (continued). "Nevertheless, HOTTIP, miR-27a-3p, and GNG12 are all potential therapeutic targets for osteosarcoma." (PMID 34691083, 2021). "Despite this link, few studies have explored the role of GNG12 in osteosarcoma." (PMID 34691083, 2021). "Although these results suggest that HOTTIP may regulate GNG12 through ceRNA and is involved in osteosarcoma progress, further experimental studies are needed to confirm these conclusions." (PMID 34691083, 2021). "G protein subunit gamma 12 (GNG12) is observed in some types of cancer, but its role in osteosarcoma is unknown." (PMID 34691083, 2021). "Therefore, in this study, we hypothesized that GNG12 expression may influence osteosarcoma progression." (PMID 34691083, 2021). "We found that GNG12 may promote osteosarcoma through regulating ER function." (PMID 34691083, 2021). "Finally, we did not verify our findings using in vitro or in vivo experiments, meaning that the exact mechanisms of GNG12 involvement in osteosarcoma remain unclear." (PMID 34691083, 2021). "Six of these genes are increased (MYOM2, VEGFA, MUC1, IHH, GLI1 and GRIA1) and seven are decreased (VCAM1, EGFR, GPC3, IGF2, GNG12, GNGT1 and C3) in localized patients with poor prognosis that either relapse or die due to osteosarcoma." (PMID 38538763, 2024). "We found that MMP12 expression is negatively correlated with GNG12 expression, and high MMP12 expression can also predict poor osteosarcoma PFS." (PMID 34691083, 2021). "GNG12 was inhibited in metastatic osteosarcoma compared with non-metastatic osteosarcoma, and its expression predicted survival of patients (1, 3, and 5-year AUCs were 0.961, 0.826, and 0.808, respectively)." (PMID 34691083, 2021). "Therefore, GNG12 may inhibit M2 polarization of TAMs, which negatively regulates MMP12 expression and thus suppresses osteosarcoma metastasis." (PMID 34691083, 2021). "In addition, GNG12 expression was lower in metastatic than in non-metastatic osteosarcoma; patients with metastatic osteosarcoma have a poor survival prognosis." (PMID 34691083, 2021). "However, a role for GNG12 and GNG4 in the mechanism of osteosarcoma progression has not been reported, which also provides a new direction for osteosarcoma research." (PMID 36685868, 2022).
pancreatic cancer (3 papers, 2020 to 2022). "For example, Juan Li confirmed that GNG12, as an oncogene in pancreatic cancer and lung cancer, was closely associated with clinical features, and predicted poor prognoses in patients." (PMID 35928884, 2022). "Given that GNG12 is involved in modulating inflammatory responses, we further explored the underlying mechanism of GNG12‐induced pancreatic cancer cell proliferation." (PMID 31898405, 2020). "Our data indicate that GNG12 increased in PDAC specimens, and overexpressed GNG12 was associated with poor prognosis of pancreatic cancer." (PMID 31898405, 2020). "For example, GNG12 can promote pancreatic cancer cell growth in vitro and in vivo by activating the NF-βB/PD-L1 signaling axis." (PMID 35928884, 2022). "Our data show that there were higher mRNA expression levels of GNG12 in pancreatic cancer cell lines, especially in MIA Paca‐2, PANC‐1 and BxPC‐3 cells, than in HPDE6‐C7 cells (normal human pancreatic duct epithelial cells)." (PMID 31898405, 2020). "In this study, we revealed that GNG12 acted as an activator of the NF‐κB pathway in pancreatic cancer cells, but the specific mechanism needs to be studied further." (PMID 31898405, 2020). "First, we knocked down GNG12 with shRNAs in pancreatic cancer cells and subjected the cells to the MTS and colony formation assays." (PMID 31898405, 2020). "In contrast, overexpressed GNG12 up‐regulated these genes’ expression in pancreatic cancer cell lines." (PMID 31898405, 2020). "Because GNG12 in cancer is poorly understood, especially in pancreatic cancer, we first evaluated the mRNA expression of GNG12 in pancreatic cancer cell lines and normal human pancreatic duct epithelial cells." (PMID 31898405, 2020). "In this study, we demonstrated that GNG12 increased PD‐L1 transcriptionally and modulated the immune response to pancreatic cancer." (PMID 31898405, 2020). "Intriguingly, knocking down GNG12 down‐regulated the protein and mRNA levels of PD‐L1 transcriptionally in pancreatic cancer cells." (PMID 31898405, 2020). "Our findings show that overexpressed GNG12 promotes cancer cell proliferation and activates the NF‐κB signaling pathway and immune response in pancreatic cancer." (PMID 31898405, 2020). "Our data showed that knocking down GNG12 significantly inhibited pancreatic cancer cell growth in vitro." (PMID 31898405, 2020). "Notably, GNG12 overexpression regulates PD-L1 expressions by activating the NF-κB signaling pathway and promoting the proliferation of pancreatic cancer cells, thus leading to a poor prognosis." (PMID 35928884, 2022). "Therefore, our data suggest that GNG12 increases in PDAC, and overexpressed GNG12 correlates with unfavorable prognosis in pancreatic cancer." (PMID 31898405, 2020). "In summary, we studied the biological role of GNG12 in pancreatic cancer." (PMID 31898405, 2020). "Besides, we found that there were positive correlations between these genes and GNG12 levels in pancreatic cancer specimens." (PMID 31898405, 2020). "Collectively, our findings suggest that GNG12 may be suitable as a new prognosis‐related biomarker and a promising target for treatment of pancreatic cancer." (PMID 31898405, 2020). "We subsequently show that GNG12 promotes pancreatic cancer cell growth in vivo and in vitro, as evaluated using 3‐(4,5‐dimethylthiazol‐2‐yl)‐5‐(3‐carboxymethoxyphenyl)‐2‐(4‐sulfophenyl)‐2H‐tetrazolium, inner salt assays, colony formation assays and a xenograft mouse model." (PMID 31898405, 2020). "GNG12 promoted pancreatic cancer cell growth in vivo and in vitro." (PMID 31898405, 2020). "Therefore, we suggest that GNG12 might be a new prognosis‐related biomarker and a promising candidate for pancreatic cancer treatment." (PMID 31898405, 2020).
pancreatic cancer (continued). "Furthermore, our data indicated that the repression of GNG12 resulted in decreased nuclear portions of p65 in PANC‐1 and BxPC‐3 cells, but the overexpression of GNG12 led to increased p65 in the nucleus, which might be an indicator of how GNG12 activates NF‐κB signaling in pancreatic cancer." (PMID 31898405, 2020). "In this study, we showed that GNG12 increased in pancreatic cancer patient specimens compared with the nontumor pancreatic tissues." (PMID 31898405, 2020).
colorectal cancer (2 papers, 2022 to 2023). A primary or metastatic malignant neoplasm that affects the colon or rectum. "HNF4G is overexpressed in colorectal cancer (CRC) and promotes CRC cell proliferation via the PI3K/AKT pathway by targeting G protein subunit gamma 12 (GNG12) and protein tyrosine kinase 2 (PTK2)." (PMID 35240026, 2022).
endometrial cancer (2 papers, 2017 to 2021). Primary or metastatic malignant neoplasm involving the endometrium (mucous membrane that lines the endometrial cavity). "The first association of GNG12 with cancer was a study showing that low GNG12 expression increases the proliferation of endometrial cancer." (PMID 34691083, 2021). "For example, GNG12 is found to be down-regulated in endometrial cancer." (PMID 28800781, 2017).
melanoma (2 papers, 2019 to 2024). A malignant, usually aggressive tumor composed of atypical, neoplastic melanocytes. "S100A10 and GNG12 proteins are known to play roles in melanoma malignancy and the expression levels of these two proteins were higher in WM989 melanoma cells from both BCP and SCP datasets." (PMID 38621647, 2024).
pancreatic ductal adenocarcinoma (2 papers, 2020 to 2021). An infiltrating adenocarcinoma that arises from the epithelial cells of the pancreas. "A previous study showed that GNG12 did regulate PD-L1 expression by activating NF-κB signaling in pancreatic ductal adenocarcinoma." (PMID 34222011, 2021). "Guanine nucleotide‐binding protein subunit gamma‐12 (GNG12) expression was observed to be higher in pancreatic ductal adenocarcinoma patient specimens than in nontumor pancreatic tissues, and high expression of GNG12 was associated with poor prognosis." (PMID 31898405, 2020).
schizophrenia (2 papers, 2019 to 2022). A major psychotic disorder characterized by abnormalities in the perception or expression of reality. "Further mediation analyses showed some evidence of cg25189904 in GNG12 gene mediating the effect of exposure to maternal smoking on schizophrenia-related outcomes." (PMID 31262328, 2019).
asthma (1 paper, 2020). "Meanwhile, in an independent dataset of GSE123750, we found that TTC19 (P = 0.0078), TLR6 (P = 0.0086), and GNG12 (P = 0.045) were significantly expressed in severe asthma by comparison with mild-moderate asthma." (PMID 33066754, 2020).
breast carcinoma (1 paper, 2019). "Network analysis on the cancer genome atlas (TCGA) breast cancer dataset revealed interaction between CXCL12 and CXCR7 (ACKR3), and a number of G-protein family members (GNG5, GNB4, GNB2, GNG12, GNG7, GNGT1, and GNAI3)." (PMID 30993013, 2019).
cocaine addiction (1 paper, 2022). "There were 13 genes enriched in cocaine addiction and the circadian entrainment signaling pathway (Bdnf, Gnai1, Gnai3, Grin2d, Grm2, Maob, Cam2, Camk2g, Gng12, Mapk1, Pcb4, Prkm2, and Pdyn)." (PMID 36164400, 2022).
colon cancer (1 paper, 2025). "It has been demonstrated that GNG12 influences tumor immune evasion, cell proliferation, and migration, indicating that it is a potential oncoprotein in the tumorigenesis of colon cancer." (PMID 41155306, 2025).
diffuse large B-cell lymphoma (1 paper, 2022). "GNG12 was highly expressed in various tumors, including glioblastoma multiforme (GBM), lymphoid neoplasm diffuse large B-cell lymphoma (DLBC), pancreatic adenocarcinoma (PAAD), and thymoma (THYM)." (PMID 35928884, 2022).
Pleural effusion (1 paper, 2021). The presence of an excessive amount of fluid in the pleural cavity. "GNG12 and ITGA2 have been reported to relate to T/NK cells in pleural effusion." (PMID 34575089, 2021).
cancer (17 papers, 2017 to 2025). A tumor composed of atypical neoplastic, often pleomorphic cells that invade other tissues. "On this concept a recent study reported that silencing the transducer and transmembrane-signal regulator (GNG12) gene leads to the downregulation of the PD-L1 gene transcription, thus, GNG12 can be suggested as a cancer risk factor and can be considered as a possible immunotherapy target." (PMID 38468968, 2024). "GNG12 is a risk factor for several cancers, and a possible target for immunotherapy." (PMID 37189064, 2023). "Moreover, WNT16 and GNG12 were implicated as potential cancer drivers (p = 0.06 and p = 0.0006, respectively)." (PMID 32384699, 2020). "GNG12 is participated in the activation of the NF-kB signal, supporting the evasion of cancer immunity and in turn activating cancer proliferation, and angiogenesis." (PMID 37189064, 2023). "GNG12 was related to some signaling pathways that participate in the occurrence and development of cancer." (PMID 35928884, 2022). "The transducer and transmembrane-signal regulator GNG12 plays an important role in cancer progression through enhancing cell proliferation." (PMID 34691083, 2021). "Porphyromonas gingivalis-induced UCHL3 may promote cancer progression by activating the NF-κB signaling pathway, which is mediated by the substrate protein GNG12, a guanine nucleotide-binding protein involved in various cellular signal transduction pathways." (PMID 41155306, 2025). "Third, some experiments have concluded through mass spectrometry and protein blotting that UCHL3 may interact with GNG12 (G protein subunit gamma 12, a special G protein-coupled receptor that can participate in cancer immunity." (PMID 40843171, 2025). "Similar to GNG12, most of the existing researches focusing on this gene are related to cancers, and the knowledge regarding the role of CYBRD1 in MS remains unclear." (PMID 35281467, 2022). "Researchers have demonstrated that GNG12 could regulate cancer cell proliferation, inflammatory response, and immune response via activating the mTORC1 pathway and NF-κB signaling pathway." (PMID 35116059, 2021). "The cancer‐related function and clinical relevance of GNG12 in PDAC have remained unknown so far, but identifying them would be of massive significance toward finding a new treatment." (PMID 31898405, 2020). "Therefore, GNG12 may influence the development and progression of malignant tumors, and may be used as a potential biomarker for prognostic evaluation and treatment." (PMID 35928884, 2022). "On the other hand, the upregulated genes, such as GNG12, GNG4, WNT9A, EDNRB, FGF18, LAMA3, MMP2, etc., were found in pathways in cancer." (PMID 36239109, 2022). "Furthermore, GNG12 may have prognostic and therapeutic value for this cancer." (PMID 34691083, 2021). "This analysis identified 11 potential cancer drivers in the WNT signaling cascade, three of which were identified by oncodriveCLUST (RNF43: p = 7.22 × 10−6, MEN1: p = 0.02, and GNG12: p = 0.012)." (PMID 32384699, 2020). "Although there have been no studies evaluating the correlation between GNG12 and immune cells, the correlation between single genes and cancer immunity has been extensively studied." (PMID 35928884, 2022). "Furthermore, we analyzed the correlation of the mRNA levels between GNG12 and PD‐L1 (also known as CD274) using The Cancer Genome Atlas datasets and GEPIA web tool." (PMID 31898405, 2020). "However, the cancer‐related function and clinical relevance of GNG12 in PDAC have not previously been reported." (PMID 31898405, 2020). "Although our study is the largest to date to assess WNT regulators in BRAF mutant cancers, we did not have a sufficiently large enough sample size to draw conclusions as to the prognostic implications of genes that are mutated more rarely, such as MEN1 and GNG12." (PMID 32384699, 2020).
tumor (14 papers, 2018 to 2025). "GNG12, a particular G protein-coupled receptor, which plays crucial roles in the proliferation of tumor cells as a transducer and transmembrane signaling regulator." (PMID 36309699, 2022). "The correlation between GNG12 expression levels and tumor immune cell infiltration was analyzed using the TIMER database." (PMID 35928884, 2022). "The results showed that GNG12 was enriched in tumor-related pathways, including the cell adhesion molecule signaling pathway, JAK-STAT signaling pathway, TOLL-LIKE receptor signaling pathway, focal adhesion, VEGF signaling pathway, and MAPK signaling pathway." (PMID 35928884, 2022). "Immune infiltration analysis demonstrated that GNG12 regulated the proportions of macrophages (M0, M1, and M2) and mast cells to influence the tumor microenvironment." (PMID 34691083, 2021). "Patients with low tumor expression of GNG12, HBP1 and SESN1 genes presented reduced OS and worse RFS, compared to patients with high expression of these genes." (PMID 34681793, 2021). "Furthermore, UCHL3 interacts with and stabilizes GNG12, activating the NF-κB pathway that leads to PD-L1 upregulation and promotes tumor development." (PMID 40843171, 2025). "GNG12 promotes tumor progression by up-regulating PD-L1 through activation of the NF-κB pathway." (PMID 40843171, 2025). "In addition, there are other studies have confirmed that GNG12 participate in inflammation signals, related to tumor immunity." (PMID 38324550, 2024). "However, the expression of GNG12 in the tumor cells was significantly lower than that in the normal cell line." (PMID 36212395, 2022). "We used an ROC curve to analyze whether GNG12 expression could distinguish between 15 normal samples and 103 tumor samples from the GEO dataset." (PMID 34691083, 2021). "We also showed that GNG12 promoted PDAC tumor growth in vivo and in vitro." (PMID 31898405, 2020). "Reducing GNG12 expression levels may inhibit tumor cell proliferation and invasion." (PMID 35928884, 2022). "Furthermore, PANC‐1 cells with or without knocked‐down GNG12 were transfected into nude mice subcutaneously for the xenografts assay, to verify the tumor growth‐promoting effect of GNG12." (PMID 31898405, 2020).
infection (1 paper, 2020). The state of being infected such as from the introduction of a foreign agent such as serum, vaccine, antigenic substance or organism. "We speculate that hypermethylated GNG12 epigenotype may predispose subjects to infection with Mtb and poorer outcomes by dampening host immune responses." (PMID 32365959, 2020).
neurodegenerative disease (1 paper, 2018). A disorder of the central nervous system characterized by gradual and progressive loss of neural tissue and neurologic function. "Gng12 is a negative modulator of LPS induced inflammation in neurodegenerative diseases." (PMID 29888212, 2018).
GNG12 also shares sentences with these, for which no sentence is quoted: abortion (1 paper); alcoholism (1); atherosclerosis (1); glioblastoma multiforme (1); Huntington disease (1); inflammatory bowel disease (1); invasive breast carcinoma (1); liver cancer (1); lung carcinoma (1); lymphoid neoplasm (1); pancreatic adenocarcinoma (1); pulmonary TB (1); thymoma (1); type A thymomas (1).